ECH1 (enoyl-CoA hydratase 1)
Description:
Auxiliary enzyme in the beta-oxidation of mono- and polyunsaturated fatty acids. Together with the 2,4-dienoyl-CoA reductase (DECR) and the Enoyl-CoA delta isomerase 1 (ECI1) they allow reentrance of the enoyl-CoA into the beta-oxidation cycle. Able to isomerize 3-trans,5-cis-dienoyl-CoA (3E,5Z-dienoyl-CoA) to 2-trans,4-trans-dienoyl-CoA (2E,4E-dienoyl-CoA), a crucial step in the beta-oxidation of unsaturated fatty acids with double bonds at odd position (By similarity). Based on its established catalytic mechanism, it is predicted to act also on other fatty acids besides those tested experimentally (Probable).
Synonyms: HPXEL
Tractability: Small molecule: it has a binding pocket of medium quality. PROTAC: ubiquitination databases record sites on it; its protein half-life has been measured; a small molecule that binds it is known.
Target class: Isomerase; Enzyme
Gene: Protein-coding gene on chromosome 19 (38,815,417 to 38,831,874, reverse strand). Ensembl gene ENSG00000104823.
Subcellular location: Mitochondrion; Peroxisome
Subcellular location (Human Protein Atlas): Mitochondria
Pathways (Reactome):
Metabolism of proteins: Mitochondrial protein degradation
Protein localization: Peroxisomal protein import
Gene Ontology:
Molecular function: protein binding; catalytic activity; delta(3,5)-delta(2,4)-dienoyl-CoA isomerase activity; isomerase activity
Biological process: fatty acid beta-oxidation
Cellular component: extracellular exosome; membrane; mitochondrion; cytosol; mitochondrial matrix; peroxisomal matrix; peroxisome; cytoplasm
Genetic constraint (gnomAD): Loss-of-function variants: 32 observed, 39.67 expected, observed/expected ratio (o/e) 0.81, 90% interval 0.61 to 1.08. The upper end of that interval is the gene's LOEUF score, 1.08, which puts it in group 4 of 6, group 1 being the genes least tolerant of losing a copy. Missense variants: 456 observed, 446.68 expected, observed/expected ratio (o/e) 1.02, 90% interval 0.94 to 1.1. Synonymous variants: 178 observed, 179.55 expected, observed/expected ratio (o/e) 0.99, 90% interval 0.88 to 1.12.
Homologues: Orthologues: chimpanzee ECH1 (99% identical), pig ECH1 (77% identical), rat Ech1 (76% identical), mouse Ech1 (74% identical), tropical clawed frog ech1 (63% identical), zebrafish ech1 (60% identical), Drosophila melanogaster CG9577 (45% identical), Caenorhabditis elegans F58A6.1 (38% identical). Paralogues in human: ECHDC2 (28% identical), AUH (23% identical), ECHS1 (23% identical), CDYL (21% identical), CDYL2 (21% identical), CDY2A (20% identical), CDY2B (20% identical), CDY1B (19% identical), ECHDC3 (19% identical), CDY1 (18% identical), ECI1 (18% identical), ECHDC1 (17% identical), and 1 more.
Diseases named in the same sentence as ECH1 in open-access papers:
ECH1 is named in the same sentence as 25 diseases in open-access papers, as found by Europe PMC text mining. Sharing a sentence is not in itself a finding about the gene and the disease. The quoted sentences say what the papers report.
Hepatic steatosis (3 papers, 2014 to 2023). Steatosis is a term used to denote lipid accumulation within hepatocytes. "Enoyl coenzyme A hydratase 1 (ECH1) treatment in the MCD-induced NASH mice was confirmed to mitigate hepatic steatosis and liver damage by blocking ferroptosis." (PMID 36992907, 2023). "ECH1 overexpression was able to ameliorate hepatic steatosis, fibrosis, and liver damage in the MCD-induced NASH model mice via the inhibition of ferroptosis." (PMID 36992907, 2023). "The downregulation of Ech1 contributes to high-fat diet-induced hepatic steatosis." (PMID 25197313, 2014). "Studies have shown that ECH1 knockdown can aggravate liver steatosis, inflammation, and fibrosis in mice, while ferrostatin-1 intervention can alleviate the pathological changes aggravated by ECH1 knockdown, suggesting that ECH1 may slow the progression of NASH in mice by inhibiting ferroptosis." (PMID 35720113, 2022). "Previously, ECH1 has been confirmed to mitigate HFD-induced IR and hepatic steatosis directly by restraining the expression of lipogenesis genes and by repressing the insulin pathway via the attenuation of Akt phosphorylation." (PMID 36992907, 2023).
glioma (2 papers, 2024 to 2025). A benign or malignant brain and spinal cord tumor that arises from glial cells (astrocytes, oligodendrocytes, ependymal cells). "Together, these results demonstrate that ECH1 depletion impeded the oxidation of PUFAs and stimulated lipid peroxidation in glioma cells." (PMID 39932808, 2025). "The expression level of ECH1 was not significantly different in different grades of gliomas." (PMID 39932808, 2025). "Notably, mRNA levels of ECH1 were not significantly changed between low-grade glioma and GBM tumors." (PMID 39932808, 2025).
Obesity (2 papers, 2024 to 2025). Accumulation of substantial excess body fat. "Much evidence suggests that ECH1 regulates nonalcoholic fatty liver disease, type 2 diabetes, and obesity." (PMID 38946717, 2024).
aortic valve calcification (1 paper, 2024). "Here, we demonstrated for the first time that ECH1, which is mostly expressed in interstitial valve cells, was decreased in human CAVs and tend to slow aortic valve calcification development in vivo." (PMID 38946717, 2024). "Therefore, our study provides novel insights into the molecular mechanism regulating Wnt5a/Ca2+ in the pathogenesis of CAVD, targeting ECH1 may prove of therapeutic potential to aortic valve calcification." (PMID 38946717, 2024).
aortic valve disease (1 paper, 2016). "The expressions of ACADM, FABP3, ECH1, ACAA2, EHHADH and CPT1A in the left atria were significantly up-regulated in the MR patients with heart failure compared to patients with aortic valve disease and heart failure and normal controls." (PMID 27250500, 2016). "Notably, only ACADM, FABP3, ECH1, ACAA2, EHHADH, CPT1A and PLTP of the PPAR pathway were significantly differentially expressed in the MR patients compared to patients with aortic valve disease and normal controls." (PMID 27250500, 2016). "Notably, only ACADM, FABP3, ECH1, ACAA2, EHHADH, CPT1A and PLTP of the PPAR signaling pathway were differentially expressed in the left atria of MR patients compared to patients with aortic valve disease and normal controls." (PMID 27250500, 2016). "Notably, seven genes (ACADM, FABP3, ECH1, ACAA2, EHHADH, CPT1A and PLTP) of the PPAR signaling pathway were differentially expressed in the left atria of MR patients compared to patients with aortic valve disease and normal controls." (PMID 27250500, 2016).
breast carcinoma (1 paper, 2026). "For ACSM3, ECH1, and SUCLG1, no prior association with breast cancer has been reported." (PMID 41517855, 2026).
calcification (1 paper, 2024). Process by which organic tissue becomes hardened by the physiologic deposit of calcium salts. "Overexpression of ECH1 reduced aortic valve calcification, while CHIR‐99021, a Wnt agonist, may significantly lessen the protective impact of ECH1 overexpression on the development of valve calcification." (PMID 38946717, 2024).
glioblastoma (1 paper, 2025). The most malignant astrocytic tumor (WHO grade IV). "al. demonstrate that TRAF3 loss promotes ECH1-mediated oxidation of polyunsaturated fatty acid (PUFA) and protects glioblastoma cells from lipid peroxidation damage." (PMID 39932808, 2025).
hyperlipidemia (1 paper, 2025). "In that study, HFD caused hyperlipidemia and increased oxidative stress, and Ech1 was one of the most significant common cardiac and aortic expressed proteins." (PMID 41203872, 2025).
hyperuricemia (1 paper, 2023). An abnormally high level of uric acid. "In addition to this mechanism of triglyceride synthesis using excess carbohydrate, hyperuricemia may lead to a decrease in the activity of the enzyme enoyl CoA hydratase 1, a key enzyme in the beta-oxidation process of fatty acids." (PMID 37760978, 2023).
overnutrition (1 paper, 2019). An imbalanced nutritional status resulting from excessive intake of nutrients. "Overnutrition suppressed enoyl-CoA hydratase-1 (ECHS1) activity and linked to increased risk of cancer." (PMID 31258820, 2019).
Stroke (1 paper, 2025). Sudden impairment of blood flow to a part of the brain due to occlusion or rupture of an artery to the brain. "Subsequently, Mendelian randomization identified a causal relationship between ECH1 and stroke." (PMID 40918984, 2025). "Mendelian randomization analysis further confirmed the causal association between ECH1 and stroke." (PMID 40918984, 2025). "Third, as a cross-sectional study conducted at a single time point, it lacks longitudinal tracking of ECH1 dynamics during stroke onset and progression." (PMID 40918984, 2025). "Notably, ECH1 showed a negative estimate effect in the MR results, indicating a relationship between decreased expression and increased Stroke risk, which showed a high consistency with the transcriptome results (ECH1 only; the other two genes were excluded because of the opposite result)." (PMID 40918984, 2025). "Our results showed that ECH1, MAPK14, and BRD2 were significantly correlated with stroke, and no pleiotropy or heterogeneity was detected (P < 0.05)." (PMID 40918984, 2025).
tumor (8 papers, 2012 to 2025). "In conclusion, our study demonstrated that loss of TRAF3 in GBM induced mitochondrial translocation of ECH1 and oxidation of PUFAs, thereby inhibiting lipid peroxidation, and promoted tumor growth." (PMID 39932808, 2025). "By targeting the TNF receptor–associated factor 3/enoyl-CoA hydratase 1 (TRAF3/ECH1) axis, they revealed an innovative approach to disrupt tumor metabolism while enhancing antitumor immunity." (PMID 40166928, 2025). "In the present study, we demonstrate that the loss of TRAF3 in GBM activated ECH1-mediated metabolism of PUFAs, thereby inhibiting lipid peroxidation and promoting tumor growth." (PMID 39932808, 2025). "Double repression of ACSL4 and enoyl-CoA hydratase 1 (ECH1) markedly reversed the metastasis of tumor cells." (PMID 41188993, 2025). "Downregulation of enoyl-CoA hydratase 1 (ECH1) inhibits Hca-F cells’ ability to metastasize to peripheral lymph nodes in vivo, thereby inhibiting the development and progression of tumor metastasis." (PMID 36892747, 2023). "Therefore, TRAF3/ECH1 axis–regulated PUFA metabolism controlled the energy supply on the one hand, and modulated the vulnerability of tumor cell to T cell–mediated cell killing on the other hand." (PMID 39932808, 2025). "In an orthotopic xenograft GBM model, ECH1 depletion in GBM0709 and GBM0108 cells resulted in significant inhibition of tumor growth and a considerable prolongation of the survival of GBM tumor–bearing mice." (PMID 39932808, 2025). "In a landmark study, ClpP was identified among a subset of deregulated mitochondrial enzymes, alongside cytochrome c oxidase subunit 5A (COX5A) and enoyl-CoA hydratase 1 (ECH1), suggesting impairments in redox homeostasis, mitochondrial protein quality control, and metabolic rewiring in tumor cells." (PMID 41155556, 2025).
cancer (6 papers, 2012 to 2025). A tumor composed of atypical neoplastic, often pleomorphic cells that invade other tissues. "In these cancer cells, enoyl-CoA hydratase-1 (ECHS1), a key enzyme in BCAA metabolism, is downregulated." (PMID 40437561, 2025). "Over-expression of ECH1 can enhance the energy generation, and promote adhension and migration capability of cancer cell for cancer metastasis." (PMID 23217164, 2012). "More interestingly, seven different genes (ECH1, PEX5, MLF2, NFIX, TSPAN9, SAMD4B, and NFKBIB) were associated with another drug C646, which is a small molecule inhibitor targeting histone acetyltransferase p300, an enzyme that alters the cancer transcriptome in the lung, colon and pancreas." (PMID 29207666, 2017). "Our results confirmed the enhancement of fatty acid biosynthesis pathway and upregulation of Fasn, Ech1, Acaa2 and Hadh, four metabolic genes in the pathway, in KAR cancer cells." (PMID 40621620, 2025). "Additionally, fatty acid metabolism‐related genes, including Acaa2, Mdh2 and Ech1, as well as oxidative phosphorylation‐related genes, such as Sdhc, Cox5a and Mdh1, also upregulated in KAR cancer cells." (PMID 40621620, 2025).
ECH1 also shares sentences with these, for which no sentence is quoted: liver cancer (3 papers); COVID-19 (1); Dystonia (1); gastric carcinoma (1); heart failure (1); idiopathic dilated cardiomyopathy (1); ischemic stroke (1); lung carcinoma (1); nonalcoholic fatty liver disease (1); osteoporosis (1); type 2 diabetes (1).